CCR6 (C-C motif chemokine receptor 6)
Diseases named in the same sentence as CCR6 in open-access papers (continued):
Sharing a sentence is not in itself a finding about the gene and the disease.
tumor (continued). "Accordingly, bulk RNAseq analysis from tumor tissues unveiled a down-regulation of several genes that are related to B cell activation in CoPEC-positive tumors, such as CD19, CCR6, CD40LG and DOCK11." (PMID 38417029, 2024). "The coordinated actions of CCR6 and CCL20 contribute to tumour progression by exerting multiple functions on both HCCs and ECs." (PMID 38493218, 2024). "It binds to miR-1322, enhancing CCL20 secretion, which interacts with CCR6 on TAMs, facilitating tumor cell and TAM communication that promotes tumor progression." (PMID 38249783, 2024). "To confirm that RANKL/RANK signaling recruits Tregs via the CCL20–CCR6 pathway, we discovered that CCR6 and FOXP3 were colocalized in the blood and tumor tissue of CRC." (PMID 38902257, 2024). "For lymphoid cells, we found an increased expression of the cytokine receptors CCR6 and CXCR3 in memory T cells from both benign disease and tumor patients." (PMID 38686549, 2024). "Meanwhile, tumour cells secrete various growth factors, including CCL20, which can bind to its specific receptor, CCR6, to accelerate the development of cancer by inducing angiogenesis." (PMID 38493218, 2024). "In vivo studies with CCR6-deficcient GBM xenografts showed reduced vascularisation, slow tumour growth, and lower expressed levels of HIF-1α compared to control (CCR6 positive)." (PMID 37686652, 2023). "Statistically insignificant correlations were observed between CCR6 and CCL20 mRNA expression levels and tumor size (p > 0.05, Kruskal–Wallis test)." (PMID 37316552, 2023). "Instead, overexpression of CCR6 in the MC38-ova model was sufficient and even superior over T cells co-transduced with other tumor-homing receptors." (PMID 37301772, 2023). "CCL20 promotes the attraction of CCR6+ T cells to tumor sites expressing CCL20 and CCR6+ cancer cells to metastatic sites with abundant CCL20." (PMID 37092451, 2023). "We confirmed that specific and differential pattern of CCR6, CCR7 mRNA expression levels was manifested in NSCLC tumor cells." (PMID 37316552, 2023). "The aim of present study was to assess changes in both the expression levels of CCR6 and CCL20 in tumor tissue of NSCLC patients and the expression level of miR-150, that is known to regulate the expression level of CCR6 according to data-base mirTarBased." (PMID 37316552, 2023). "Here, an epidermal growth factor receptor (EGFR) CAR-T cell was engineered to express the chemokine receptor CCR6 and secrete PD1 blocking Single-chain antibody fragment (scFv) E27 to enhance their anti-tumor effects." (PMID 36982500, 2023). "These activated CCR6+ILC3s can secrete CXCL10 that promotes CD4+ and CD8+ T cells migration to the tumor, enhancing anti-tumor immunity and response to immune checkpoint blockade." (PMID 36341381, 2022). "Following our earlier observations of elevated CXCL11 and CCL20 transcripts in the tumor epithelial compartment, we observed a positive correlation with the expression of their respective receptors, CXCR3 and CCR6, in the microenvironment." (PMID 35394843, 2022). "The mechanism by which CD45RO+CCR6+CD4+ cells and granulocytes are recruited in TME is likely related to the presence of elevated amounts of IL-6 in tumor secretome from SD OSCC patients." (PMID 36713516, 2022). "As the tumor size increases, the presence of CD4+ CCR6+ CCR5+ CXCR3− and CD4+ CCR6+ CCR5− CXCR3− T cells also increase, which means that Th17/Th1 and Th17 cells’ presence is directly correlated with the size of the tumor in CRC liver metastasis." (PMID 36551555, 2022). "For instance, CCR6 is found significantly overexpressed in CRC tissues and facilitates tumor angiogenesis via the AKT/NF-κB/VEGF pathway." (PMID 35935996, 2022). "bulgaricus OLL1073R-1 (EPS-R1) induced CCR6+ CD8+ T cells in Peyer’s patches and fostered the infiltration of these cells into CCL20-expressing tumor tissues in mouse models." (PMID 36726985, 2022).
tumor (continued). "CCL20 thus allows the recruitment of CCR6+ CD4 immunosuppressive T cells (Th17, Treg) at the tumor site and favors the migration and the metastatic potential of CCR6-expressing cancer cells from diverse types." (PMID 36429101, 2022). "Remarkably, whatever the tumor stage (early [I and II] and advanced [III and IV], the percentages of CD45RO+CCR6+ cells were increased in SD patients as compared to NSND patients, whereas the percentages of Treg were similar." (PMID 36713516, 2022). "CircSMARCC1 up-regulates the chemokine CCL20 secretion by sponging miR-1322, which is involved in the crosstalk between tumor cells and TAMs by targeting CCL20/CCR6 signaling to promote progression of PCa." (PMID 36045408, 2022). "In CCL20-expressing tumor bearing mice, EPS-R1 induced CCR6 expression in CD8+ T cells by binding to lysophosphatidic acid receptor on cells." (PMID 35956752, 2022). "Our study found that F. nucleatum enhances tumor-derived CCL20 expression and recruits F4/80+ CCR6+ macrophage in the TME." (PMID 34632963, 2021). "Consistent with in vitro and Luminex assays results, tumor tissues derived from LN229 ADO-Cas9 cells displayed conspicuously lower levels of CCL20 and CCR6 compared to the control group." (PMID 33483477, 2021). "Flow cytometry analysis of 344SQ and 393P tumor tissues showed an increase in CCR5+, CCR6+, and IL-17+RORγt+ CD4+ T cells in tumors that developed resistance to therapy." (PMID 33972557, 2021). "In particular, they showed that IL-6 production can shape macrophages towards a tumor-promoting phenotype, which stimulates lymphocyte recruitment through the CCL20/CCR6 (C-C Motif Chemokine Receptor 6) axis, finally leading to CAC development." (PMID 33513730, 2021). "Other receptors such as CCR5, CCR6, CXCR2 and CX3CR1 were mostly identified for their expression and function in immune cells from the tumor microenvironment." (PMID 35008294, 2021). "Many studies have shown that the CCL20/CCR6 axis contribute to the initiation and progression of HCC by mediating the migration of circulating T cells into the tumor microenvironment." (PMID 32256215, 2020). "Chemokine axes such as CCL19, CCL21/CCR7, CCL20/CCR6, CXCL12/CXCR4, and CXCL13/CXCR5 correlate with B cell infiltration to tumor sites." (PMID 31991604, 2020). "The same study has found that CCL20 produced by HCC cells recruits CCR6+CD5+ B cells and induces angiogenesis to promote tumor growth and that blocking CCL20 suppressed angiogenesis." (PMID 32707869, 2020). "We found that CCR6 and CCR10 were the only chemokine receptors that were more highly expressed by the CD39+ Treg in the tumor compared to the CD39− Treg." (PMID 30651930, 2018). "In both mouse and human ovarian cancers, CCR6+ cDCs are recruited massively in the TME through the tumor-derived β-defensins and are induced to become proangiogenic cells, favoring tumor vascularization, and growth in response of tumor VEGF." (PMID 29675018, 2018). "They showed overexpression of functional CCR6 and CCR7 on metastatic tumor cell lines obtained from the liver." (PMID 30004409, 2018). "In vivo, we testified gene expression in xenograft tumor from control/u50535OE mice model and found that the u50535 overexpression can upregulate CCL20 and its following signal molecules such as CCR6, ERK, AKT, NFKBIA and so on." (PMID 29970882, 2018). "But with the deepening research of the CCR6 biology function, CCR6 and CCR6-CCL20 axis are expected to become new targets for treatment of ESCC, and provide a new strategy in inhibition of tumor growth and metastasis." (PMID 29383156, 2017). "In CRC tissues, the main source of CCL20, a ligand for CCR6, is considered to be TAM, and CCL20 secreted from TAM recruits CCR6+ T-reg to the tumor site, which synergistically promotes tumor progression in mouse models." (PMID 27136535, 2016).
tumor (continued). "FACS results confirmed the activated state of FcγRIIlow/− B cells as following: most FcγRIIlow/− B cells from HCC tumours displayed a CD69+BTLA− activated phenotype with reduced B-cell follicle homing molecules CD62L, CXCR5 and CCR6." (PMID 27853178, 2016). "To next establish the role of CCR6 deletion on mammary tumorigenesis, we compared the rate and total extent of PyMT-driven neoplasia between MMTV-PyMT Ccr6WT and Ccr6−/− mice." (PMID 26047945, 2015). "Levels of tumor-infiltrating immune cells within tumor-bearing mammary glands from MMTV-PyMT Ccr6WT and Ccr6−/− mice were also analyzed." (PMID 26047945, 2015). "In agreement with the results from spontaneous tumorigenesis studies, we have found that tumors grew significantly slower in the Ccr6−/− hosts compared to Ccr6WT, indicating that CCR6 is required in the mammary stroma for robust tumor development." (PMID 26047945, 2015). "The CD44H (hyaluronian receptors), CD44v6, CCR6 (chemokine receptors) and EGFR (epithelial growth factor receptor) are involved in interactions of tumour cells with monocytes." (PMID 26626416, 2015). "Once the tumor cells have entered the blood or lymphatic vessels, the constitutive expression of CCL20 by the liver or other sites attracts a second wave of CCR6-expressing CRC cell migration." (PMID 24979261, 2014). "In addition, the chemokine receptor CCR6 [which binds to the chemokine CC ligand 20 (CCL20) that is present in many malignant pleural effusions of lung cancer patients] is highly expressed on Th17 cells thus further facilitating their recruitment to sites of tumor growth and inflammation." (PMID 23533029, 2013). "High intra-tumoral levels of CCL20 result in the accumulation of immature CCR6+ DCs within the tumor bed, whereas high peri-tumoral levels of CCL19 promote the accumulation of mature CCR7+ DCs preferentially to the tumor margin." (PMID 24339824, 2013). "And tumor-resident DC secreting TGF-β seems to be crucial for the in situ expansion and suppressive effect of CCR6+Tregs in vivo." (PMID 21655250, 2011). "To further confirm the effect of DCs on the proliferation of CCR6+Tregs, we further intratumoral injected DCs into tumor mass in 4T1 bearing syngeneic mice and found that DCs could also significantly promote the proliferation of CCR6+Tregs in tumor mass (p<0.05)." (PMID 21655250, 2011). "4a, anti-TGF-β antibody treatment significantly reduced the proliferation and frequency of CCR6+Tregs in tumor mass, suggesting TGF-β was critical for the in situ CCR6+Tregs proliferation." (PMID 21655250, 2011). "Injection of recombinant mouse CCL20 into CRC promoted tumor development with a marked recruitment of Treg-cells in wild-type mice, and stimulated tumor growth by directly activating CMT93 cells in CCR6−/− mice." (PMID 21559338, 2011). "Additionally, we encapsulated the Toll-like receptor 7/8 agonist R848 within the CCR6-modified macrophage membrane (CCR6-MM) to polarize M2-type TAMs to the M1 phenotype, reducing CCL20 secretion and transforming the immunosuppressive tumor microenvironment." (PMID 41625363, 2025). "A previous study showed that Treg cells from both the tumor microenvironment and dLNs in HNSCC patients exhibited a CCR6+ effector Treg cell phenotype, and CCR6+ Treg cells expressed a higher level of FOXP3 than CCR6− Treg cells, which indicated a stronger suppressive function." (PMID 40290124, 2025). "To identify CCR6 expression in human lung tissue samples, we performed immune-histochemical studies on tissue sections taken from lungs of patients with IPF and lung tissue from lobectomies far from the tumour." (PMID 38334630, 2024). "In contrast, lung fibroblasts from lungs of controls (i.e., tumour-free tissue from cancer patients) did not express CCR6." (PMID 38334630, 2024). "CCR6, the sole receptor of CCL20, plays a regulatory role in CCL20-induced tumour migration." (PMID 38493218, 2024).
tumor (continued). "A decreased expression of CD274 and CCR6 (p < 0.001) on non-hematopoietic cells from tumor samples when compared with non-tumor samples was observed." (PMID 37370832, 2023). "The expression of CD274 and CCR6 was also evaluated on non-hematopoietic cells present in both non-tumor and tumor samples, as well as in tumor samples with non-desmoplastic or desmoplastic growth patterns." (PMID 37370832, 2023). "Additionally, responding patients had a lower tumor burden and displayed the expression of chemokine receptors (CCR7, CCR6, CXCR4, CXCR3, and CXCR5) on CD4+ T cells." (PMID 37174069, 2023). "Additionally, CDKN2A experienced different forms of genetic alteration under tumor conditions, a characteristic that influenced the infiltration and the status of CD8, the chemokine CCL4, and the chemokine receptor CCR6." (PMID 37626750, 2023). "The roles of EPS-R1-induced CCR6+ CD8+ T cells may differ, potentially relying on tumor heterogeneity, the time and duration of ICB therapy, the content and variety of cytokines/chemokines within the tumors and other intratumoral immune cells." (PMID 36726985, 2022). "In this evaluation, we could also verify that the tumor size is significantly correlated with the presence of Th17/Th1 (CD4+ CCR6+ CCR5+ CXCR3−) and Th17 cells (CD4+ CCR6+ CCR5− CXCR3−) cells in the TME." (PMID 36551555, 2022). "A recent study also reported that RORγ agonists increased the expression of CCR6 and CCL20 in Tc17 cells, and this might contribute to the better migration of Tc17 cells into the tumor and recruitment of Tc1 cells." (PMID 35459193, 2022). "Selective recruitment of regulatory T cells (Tregs) by CCR6 and its ligand CCL20 in the tumor microenvironment may inhibit the proliferation of CD4CD25 and INF-γ secretion and promote the development of HCC." (PMID 36231045, 2022). "Ten chemokine receptors (CXCR1, CXCR2, CXCR4, CXCR6, CCR3, CCR6, ACKR4/CCRL1, CCLR2, CX3CR1, and ACKR1/DARC) were identified as differentially expressed from the DEG analysis between Black, White and Asian patient normal and tumor samples." (PMID 35754051, 2022). "Interestingly, TGF-β, which is secreted by tumor cells and tumor-infiltrating regulatory T cells, enhances the expression of chemokine receptors CCR1, CCR3, CCR5, CCR6, and CXCR4 on DCs, thereby driving DC migration to the TME." (PMID 34290401, 2021). "CCR6 interacted with CCL20 in the pCR group and is a receptor of CCL20; overexpression of CCL20 augments mitogen-activated protein kinase and protein kinase C signalling, resulting in tumour progression." (PMID 33138797, 2020). "This study by Ito and colleagues provides in vivo evidence that miR-150 is capable of suppressing tumor metastasis and invasion by targeting the chemokine receptor or CCR6, which prevents autocrine signaling in advanced CTCL, particularly IL-22-CCL20-CCR6 signaling." (PMID 33291485, 2020). "One study has shown that high CCR6 expression by circulatory Treg and directional migration toward CCL20 promote Treg migration into tumor tissue and that intratumoral CCL20 concentration and tumor-infiltrating Treg number are positively correlated." (PMID 32707869, 2020). "In contrast, B16F10 tumours grown in Ccr6−/− → Ccr6+/+ mice were not significantly larger than tumours grown in a Ccr6+/+ → Ccr6+/+ mice background." (PMID 32601464, 2020). "Interestingly, these pathways are utilized by a series of chemokines and their receptors, such as CCL20/CCR6, CCL25/CCR9, CXCL1/CXCR2, CXCL8/CXCR1-2, CXCL12/CXCR4, and CX3CL1/CX3CR1, to inhibit apoptosis and promote tumor cell growth and proliferation." (PMID 31991604, 2020). "Considering the higher expression of chemokines, including CCR5 and CCR6, which might attract EpCAM+ CD4+ T cells to the tumor sites, we determine whether EpCAM+ CD4+ T cells are present in the tumor microenvironment within CC patients using light microscopy." (PMID 31354723, 2019).
tumor (continued). "Together, these findings suggest that the CCL20/CCR6 axis might facilitate infiltration of Th17 cell in NSCLC and promote tumor progression." (PMID 31921642, 2019). "Th17 cells are recruited to tumor sites and inflammatory sites by C-C motif chemokine ligand 20 (CCL20) expressed by epithelial and stromal cells, interacting with C-C Chemokine receptor type 6 (CCR6) on Th17 cells." (PMID 31921642, 2019). "One chemokine that can drive immune cells towards the tumor is the Macrophage Inflammatory Protein-3 alpha (MIP3α; CCL20) which attracts cells expressing CCR6/CD196 such as (memory) T cells, natural killer cells and immature dendritic cells (DCs), all of which can mediate tumor regressions 16-19." (PMID 31588231, 2019). "A subsequent flow cytometry study confirmed that CCR6 is expressed on a relevant proportion of TPC-1 (bearing the RET/PTC rearrangement) and BCPAP (bearing the BRAF mutation) tumor cells, but not in normal human thyroid cells in basal conditions." (PMID 29977225, 2018). "The roles of CCL20 in cancer development, tumor promotion, and metastasis are linked to the attraction of CCR6-expessing regulatory T lymphocytes to tumor sites expressing CCL2046–49 and to the recruitment of CCR6-expressing cancer cells to metastatic sites with abundant CCL2050." (PMID 28851919, 2017). "Transplantation experiments in particular demonstrated that the presence of CCR6 in donor epithelium was not required for tumor propagation in recipient mammary glands." (PMID 26047945, 2015). "Based on that, it is reasonable to assume that CCR6 transfer between cancer cells, as exemplified by the attachment of PKH26-labelled TMV, may be a likely mechanism responsible for the enhancement of tumour growth." (PMID 26626416, 2015). "Tumor onset was significantly delayed in MMTV-PyMT Ccr6−/− mice, with some mice not developing palpable tumors until 150 days old (21 weeks) compared to a maximum onset age of 130 days old (18 weeks) for MMTV-PyMT Ccr6WT counterparts." (PMID 26047945, 2015). "The difference seen in early tumor initiation between MMTV-PyMT Ccr6WT and Ccr6−/− mice can potentially result from a difference in normal mammary development, which may then have translated into decreased hyperplasia." (PMID 26047945, 2015). "It is debatable whether enhancement of tumour growth is connected with transfer of HER-2/neu mRNA and some TMV determinants, e.g. CD44H, CD44v6, CCR6, which are known to facilitate interaction of TMV with monocytes." (PMID 26626416, 2015). "CCR6 is being identified as a potential new prognostic marker in some types of tumours and the axis of CCL20/CCR6/IL-17 may be a new therapeutic target in cancer." (PMID 26626416, 2015). "CCR6 is not expressed on peripheral blood monocytes, and is thought to only be acquired upon their differentiation into macrophages, induced by the tumor microenvironment." (PMID 26047945, 2015). "EPCs participating in neovascularization have also been reported in HCC, in which myeloid-derived EPCs (colony forming unit-endothelial cells) as early EPCs highly express CCR6 and are mobilized by the ligand CCL20 produced by HCC cells for migration and invasion of tumor stroma to form vasculature." (PMID 25110692, 2014). "To further elucidate the downstream signaling pathway involving upregulated CCR6 in CRC aggressiveness, we compared mRNA expression profiles between HCT116CCR6 and HCT116Ctr cells using a human tumor metastasis real-time PCR array containing 84 genes known to be involved in metastasis." (PMID 24979261, 2014). "In addition, we have shown that upregulated CCR6 enhanced CRC cell proliferation, migration and in vivo tumor metastasis, likely by altering the expression of tumor metastasis-related genes." (PMID 24979261, 2014). "Most interestingly, we observed that recombinant mouse CCL20 stimulated CMT93 CRC cell growth by directly activating CCR6 on tumor cells in the absence of CCR6+ TIL in CCR6−/− mice." (PMID 21559338, 2011).